PLCE1 (phospholipase C epsilon 1)
Diseases named in the same sentence as PLCE1 in open-access papers (continued):
Sharing a sentence is not in itself a finding about the gene and the disease.
esophagitis (1 paper, 2017). An acute or chronic inflammatory disease affecting the esophageal wall. "We found that PLCE1 mRNA expression levels were significantly increased in the esophagitis, compared to the normal esophageal mucosa." (PMID 28402280, 2017). "We have previously reported that PLCE1 single nucleotide polymorphism (SNP rs2274223: A5780G:His1927Arg) was linked to esophagitis, but it was not clear whether PLCE1 expression levels are associated with esophagitis." (PMID 28402280, 2017). "Interestingly, we found that PLCE1 and PRKCA mRNA levels were even more elevated in severe esophagitis, compared to mild/moderate esophagitis." (PMID 28402280, 2017). "Based on the model of esophagitis initiation and progression, we hypothesized that PRKCA might form a partnership and close correlation with PLCE1 along with the whole process of esophageal inflammation initiation, progression and tumorigenesis." (PMID 28402280, 2017).
HIV-1 infection (1 paper, 2016). The type species of lentivirus and the etiologic agent of acquired immunodeficiency syndrome (AIDS). "Soluble uPAR is a versatile signaling proteinase receptor that had been suggested as a biomarker to predict survival of HIV-1 infection and to discriminate primary focal segmental glomerulosclerosis, which may also be related to the protective PLCE1 loci associated with DSS." (PMID 27286230, 2016).
intraepithelial neoplasia (1 paper, 2016). A precancerous neoplastic process that affects the squamous, glandular, or transitional cell epithelium without evidence of invasion. "This study is the first to report that PLCE1 protein expression increased progressively from normal esophageal epithelium to low-grade intraepithelial neoplasia to ESCC and reached the highest expression level in the high-grade intraepithelial neoplasia in the Han ethnic group." (PMID 26657507, 2016).
late-onset Alzheimers disease (1 paper, 2012). This is the most common form of the disease, which happens to people age 65 and older. "Some of the other up-regulated transcripts in the VMB include members of axon guidance signaling (Rock1, Adam22), zinc finger proteins (Eif2c3 and novel KRAB box and zinc finger, C2H2 type domain containing protein) and one of the candidate genes for late onset Alzheimer's Disease (Plce1)." (PMID 22563483, 2012).
liver fibrosis (1 paper, 2025). "Furthermore, EGCG alleviates liver fibrosis by reducing intracellular calcium levels and downregulating phospholipase C epsilon 1 (PLCE1) expression." (PMID 41106481, 2025).
major depressive disorder (1 paper, 2023). An episode of depression lasting two or more weeks without an intervening episode of mania. "A previous study investigating the role of PLCE1 in major depressive disorder patients has demonstrated an association with antidepressant remission in female patients, together with other genes within the calcium/calmodulin-dependent protein kinase pathway." (PMID 36882310, 2023).
metabolic syndrome (1 paper, 2021). A cluster of metabolic risk factors for CARDIOVASCULAR DISEASES and TYPE 2 DIABETES MELLITUS. "Our PheWAS findings revealed that PLCE1 and HMGA2 could be the genetic links between age-related cataract and metabolic syndrome." (PMID 34127677, 2021).
oropharyngeal cancers (1 paper, 2011). Carcinoma, predominantly squamous cell, arising from the epithelial cells of the oropharynx. "To investigate the modifying effects of PLCE1 variants on risk of SCCHN with different tumor sites, we conducted the stratification analysis by oropharyngeal and non-oropharyngeal cancers." (PMID 21689432, 2011).
renal cell carcinoma (1 paper, 2019). "Du’s group reported that PLCE1 promotes renal cell carcinoma cell growth via the NF-κB-mediated upregulation of VEGF." (PMID 30609930, 2019). "Du’s paper discussed PLCE1 promotion of renal cell carcinoma growth via the NF-κB-mediated upregulation of VEGF." (PMID 30609930, 2019).
Thrombocytopenia (1 paper, 2023). A reduction in the number of circulating thrombocytes. "A genetic study reported associations of genetic polymorphisms (the R/R genotype of FCGR2A p.R131H and the G/G genotype of CCL2 c.-2518 A > G) with thrombocytopenia; however, our study did not reveal an association of MICB and PLCE1 variants with thrombocytopenia." (PMID 37958261, 2023).
type 2 diabetes mellitus (1 paper, 2025). A type of diabetes mellitus that is characterized by insulin resistance or desensitization and increased blood glucose levels. "The identified genes were involved in processes such as protein localization (ENSSSCG00000041063, ADIPOQ, ABCC8), enzyme-linked receptor protein signaling pathway (PLCE1, ADIPOQ), organic substance transport (ENSSSCG00000041063, ADIPOQ, ABCC8), and type II diabetes mellitus (ADIPOQ, ABCC8)." (PMID 40819340, 2025).
cancer (33 papers, 2011 to 2025). A tumor composed of atypical neoplastic, often pleomorphic cells that invade other tissues. "An increasing amount of studies have begun to explore the relationship between PLCE1 rs2274223 polymorphism and susceptibility of different cancers." (PMID 34491229, 2021). "Since then, multiple researchers investigated the relationship between PLCE1 polymorphisms and cancer risk." (PMID 30619753, 2018). "Recent years have witnessed an increasing number of studies that investigate PLCE1 polymorphisms and cancer susceptibility." (PMID 30619753, 2018). "Among all studies that investigated PLCE1 polymorphisms and cancer susceptibility, the SNPs rs2274223, rs3765524, rs753724, rs11187842, and rs7922612 were five of the most extensively studied polymorphic loci." (PMID 30619753, 2018). "The pooled odds ratios (ORs) with 95% confidence intervals (CIs) were used to evaluate relationships between the PLCE1 polymorphisms and cancer susceptibility." (PMID 30619753, 2018). "A total of 35 qualified case-control studies were included in this meta-analysis, which assessed the relationship between the PLCE1 rs2274223 polymorphism and cancer susceptibility." (PMID 30619753, 2018). "Our findings indicated that the PLCE1 rs2274223 polymorphism is significantly associated with cancer susceptibility in the overall population." (PMID 30619753, 2018). "There were eight qualified case-control studies in this meta-analysis, which assessed the relationship between the PLCE1 rs3765524 polymorphism and cancer susceptibility." (PMID 30619753, 2018). "In 2010, the results of genome-wide association studies indicated that PLCE1 is associated with cancer risk." (PMID 30619753, 2018). "Meta-analysis of the relationship between PLCE1 rs753724, rs11187842, rs7922612 polymorphisms and cancer risk." (PMID 30619753, 2018). "In the meta-analysis, we comprehensively evaluate the association between PLCE1 rs2274223 polymorphism and cancer risk through 22 studies with 13188 cases and 14666 controls." (PMID 25614244, 2015). "An increasing number of individual studies have investigated the association between PLCE1 rs2274223 polymorphism and cancer risk, but the conclusions are inconclusive." (PMID 25614244, 2015). "Simultaneously, an increasing amount of studies start to investigate the association of PLCE1 rs2274223 polymorphism on the susceptibility of different cancer." (PMID 25614244, 2015). "Because mutations in the RAS gene family are associated with approximately 30% of all human cancers, several studies have investigated the possible role of PLCE1 mutations in cancer development and progression." (PMID 23826241, 2013). "Thereafter, it was demonstrated that PLCE1 is also associated with carcinogenesis, including cancers of the intestine, bladder, skin, colon, rectum, head and neck." (PMID 23826241, 2013). "Since mutations in the RAS gene family are associated with about 30% of all human cancers, several studies have investigated the possible role of PLCE1 in cancer development and progression." (PMID 21689432, 2011). "Finally, cancer development was always driven by multiple genes mutations, so analysis of PLCE1 rs2274223 combining with other SNP on affecting LSCC susceptibility should be performed in following study." (PMID 33162810, 2020). "Moreover, future investigations are needed to explore potential roles of PLCE1 rs2274223 variant in the development of other types of cancer." (PMID 30784231, 2019). "Likewise, several meta-analyses assessed the association between PLCE1 polymorphisms and cancer risk." (PMID 30619753, 2018). "In addition, the results suggested that the PLCE1 rs3765524 polymorphism is associated with overall cancer risk under the heterozygote model (CT vs. CC)." (PMID 30619753, 2018). "Meta-analysis of the relationship between PLCE1 rs2274223 polymorphism and cancer risk." (PMID 30619753, 2018). "Meta-analysis of the association between PLCE1 rs3765524 polymorphism and cancer susceptibility." (PMID 30619753, 2018).
cancer (continued). "More recently, many studies have suggested that genetic variants in PLCE1 may serve as candidate markers for cancers and influence cancer risk." (PMID 29190930, 2017). "This meta-analysis demonstrated that PLCE1 rs2274223 A > G polymorphism may be associated with increased susceptibility to cancer, especially for ESCC." (PMID 25614244, 2015). "Therefore, we performed a meta-analysis of all eligible case-control studies to systematically estimate the effects of PLCE1 rs2274223 A > G polymorphism on the susceptibility to cancer." (PMID 25614244, 2015). "Although the PLCE1 rs2274223 polymorphism is associated with a high risk of cancers, the exact mechanism is still unknown." (PMID 25614244, 2015). "In conclusion, the meta-analysis suggests that PLCE1 rs2274223 polymorphism may be associated with increased susceptibility to cancer, especially for ESCC." (PMID 25614244, 2015). "However, the conclusions on the association between the PLCE1 rs2274223 A>G polymorphism and cancer risk are controversial." (PMID 25658482, 2015). "Stratified analyses of the PLCE1 rs2274223 A>G polymorphism on cancer risk." (PMID 24116107, 2013). "All these findings further support the biological plausibility that genetic variations, such as single nucleotide polymorphisms (SNPs) in PLCE1 that affect the gene expression or protein functions, may affect the risk of some cancers." (PMID 21689432, 2011). "The findings from GWASs and our study implied that polymorphisms of PLCE1 are likely to be associated with the development of human cancers related to tobacco and alcohol exposure, which will need the validation from large studies on different cancers." (PMID 21689432, 2011). "In addition, because of the gene-gene interaction, the influence of the PLCE1 rs2274223 A>G polymorphism might be masked or magnified by the presence of other genes which were unidentified yet in the development of cancer." (PMID 24116107, 2013). "Accumulating evidence has shown that PLCE1 promotes cell growth, migration, and metastasis in multiple human cancers, including hepatocellular carcinoma, non-small-cell lung cancer, head and neck cancer, bladder cancer, gastric cancer, and prostate cancer." (PMID 40266671, 2025). "The expression levels of PLCE1 showed large variation among tumour samples belonging to the same cancer types and exhibited low cancer-type specificity." (PMID 41290870, 2025). "Of these, phospholipase C epsilon 1 (PLCE1) has attracted our attention because of its essential role in cell growth, migration, and metastasis in various human cancers." (PMID 40266671, 2025). "Numerous studies have shown that PLCE1 plays a key role in cancer development and progression via various pathways." (PMID 40266671, 2025). "The significance of PLCE1 is shown with its role in a variety of important human malignant tumors, including skin cancer, bladder, colorectal, neck and head and ESCC cancers." (PMID 38725047, 2024). "Their studies have revealed that miR-34a functions to suppress the expression of PLCE1 and as a result, inhibit the development of cancer." (PMID 38725047, 2024). "They found that the G-allele of PLCE1 rs932764 and the G-allele of ATP2B1 rs17249754 are protective to doxorubicin-induced cardiotoxicity in pediatric cancer survivors." (PMID 36536332, 2022). "Numerous studies have suggested that PLCE1 plays a key role in the development and progression of cancer through various pathways." (PMID 31217261, 2019). "The importance of PLCE1 is demonstrated by its role in several major human malignant tumors, such as, skin, bladder, colorectal, head and neck and ESCC cancers." (PMID 29190930, 2017). "Distinct microRNAs were shown to suppress PLCE1 expression and thereby affect cancer development and patient prognosis." (PMID 28418898, 2017).
cancer (continued). "Knockdown of PLCE1 promoted the apoptosis, cytokine-induced apoptosis, and sensitivity of cancer cells to chemotherapeutic drugs but abrogated the proliferation and EMT phenotype of ESCC in vitro." (PMID 26657507, 2016). "Overexpressing PLCE1 potently stimulates cancer cell growth and invasion and promotes esophageal tumorigenesis in ESCC." (PMID 26657507, 2016). "We also determined the effect of PLCE1 knockdown on the survival of cancer cells given with Paclitaxel and 5-FU, which are chemotherapeutic drugs commonly used for clinical treatment of ESCC." (PMID 26657507, 2016). "Recent studies have reported that PLCE1 plays crucial roles in carcinogenesis and progression of several types of cancers, including cancers of the intestine, skin, bladder, colorectal and head and neck." (PMID 24116107, 2013). "It has been reported that PLCE1 has an oncogenic role in carcinogenesis of several human cancers, including SCCHN, through distinct mechanisms, such as inflammation, binding to the Ras family small GTPase, and augmentation of angiogenesis." (PMID 21689432, 2011). "Studies have reported that PLCE1 functions as an effector of Ras and plays crucial roles in carcinogenesis and progression of several cancers, including cancers of the intestine, skin, bladder, colorectal and head and neck." (PMID 21689432, 2011). "It has been well documented that PLCE1 plays a key role in cancer progression." (PMID 40266671, 2025). "Phospholipase C epsilon 1 (PLCE1) is involved in the pathogenesis of many cancers." (PMID 35765945, 2022). "Different expression profiles of PLCE1, like overexpression or down-regulation, could be found in different types of cancer, and functioned in diverse manners 9-12." (PMID 33162810, 2020). "But the link between PLCE1 and inflammation-related cancer is not well understood." (PMID 30609930, 2019). "As growing body of evidence demonstrates that the NF-κB signaling pathway plays a central role in both angiogenesis and resistance to apoptosis in cancer, we investigated whether PLCE1 participates in regulation of the NF-κB signaling pathway in ESCC." (PMID 30609930, 2019). "Recently, the involvement of PLCE1 in various cancers has become an area of intense interest." (PMID 31217261, 2019). "Our data suggest that miR-34a exerts its anti-cancer function by suppressing PLCE1." (PMID 29190930, 2017). "Although PLCE1 has been extensively studied, its role in human cancer remains controversial." (PMID 26657507, 2016). "Moreover, miR-145 was expressed at low levels in a large cohort of patients with ESCC and was inversely correlated with PLCE1 protein expression in cancer cells and tissues." (PMID 26657507, 2016). "Given only a modest effect of each SNP individually, evaluating their combined effects may help us better understand any role of PLCE1 SNPs in cancer etiology." (PMID 21689432, 2011). "Furthermore, we observed that the expression levels of PLCE1 were decreasing with more advanced stages, indicating that the repression of this gene is beneficial for cancer progression." (PMID 21909432, 2011). "Additionally, one study also showed that the positive rates of the PLCE1 protein in ESCC and GCA tissues were significantly higher than that in normal ones, suggesting a biologically plausible role of PLCE1 in carcinogenesis of human cancers." (PMID 21689432, 2011). "Therefore, PLCE1 is considered to be a potential target for cancer prevention and treatment." (PMID 31217261, 2019). "PLCE1 is a multifunctional signaling protein that may act as an oncoprotein, promoting malignant transformation of primary cell lines, tumor growth, migration, and metastasis in various human cancers." (PMID 30609930, 2019). "Numerous studies have shown the association between PLCE1 and PI3K/AKT/mTOR signaling during inflammation-association carcinogenesis, thus targeting PI3K/AKT/mTOR-mediated inflammatory pathway could be a good strategy for cancer prevention and therapy." (PMID 28402280, 2017).
cancer (continued). "Moreover, miR-145 modulated the oncogene PLCE1, which may explain why miR-145 downregulation during esophageal carcinogenesis can promote cancer progression." (PMID 26657507, 2016). "However, whether and how PLCE1 affects cancer metastasis in ESCC remain largely unknown." (PMID 40266671, 2025). "The results showed that the expression levels of both PLCE1 and PRKCA were also elevated in above cancers." (PMID 28402280, 2017). "Among the module genes, BUB1, GATM, PLCE1, NEGR1, PTGER3 and SH3RF2 were differentially expressed in three or more cancer tissues." (PMID 28694494, 2017). "These genes, such as PRKAA1, PLCE1 and MUC1, also play an important role in cancer progression and tumorigenesis." (PMID 27821817, 2017). "The present data support a tumor suppressive role of PLCD1 and PLCE1 in CRC, which for PLCD1 possibly can be explained by an epigenetic mechanism in microsatellite unstable carcinomas." (PMID 21909432, 2011). "In addition, 50% of cancer in situ showed strong staining, but 73% of invasive ESCC showed strong staining of PLCE1 (p = 0.032)." (PMID 28402280, 2017). "Promoter methylation analyses of PLCD1 and PLCE1 performed in cell lines and tumor biopsies revealed that methylation of PLCD1 can contribute to reduced expression in 40% of the microsatellite instable carcinomas." (PMID 21909432, 2011). "At first, we analyzed transcriptomic data on PLCE1 from The Cancer Genome Atlas (TCGA) using the GEPIA2 platforms, where PLCE1 mRNA levels were measured in a large number of tumour samples belonging to various cancer types and matching normal tissues and their average values were determined." (PMID 41290870, 2025). "Therefore, PLCE1 is an effective candidate biomarker and a potential therapeutic target in ESCC because it can restore cell sensitivity to apoptosis or induce apoptosis to eliminate cancer cells." (PMID 26657507, 2016). "However, the role of PLCE1 in the pathogenesis of these cancers has not yet been fully clarified and was inconsistent in different cancer." (PMID 25683757, 2015). "Importantly, we have demonstrated that PLCE1 and PRKCA are slightly expressed in normal esophageal epithelial cells, and that their expression levels are gradually increased during esophageal inflammation, progression, and malignant transformation – cancer-in-situ and invasive ESCC." (PMID 28402280, 2017).